SIRT5 (sirtuin 5)
Diseases named in the same sentence as SIRT5 in open-access papers (continued):
Sharing a sentence is not in itself a finding about the gene and the disease.
tumor (continued). "SIRT5 has recently drawn extensive attention as a highly efficient protein lysine desuccinylase and has been proven to play a vital role in the complex biological processes of tumor cells." (PMID 40164945, 2025). "Overexpression of the SIRT5 desuccinylase results in inhibition of tumor growth in these cases." (PMID 40149343, 2025). "However, current research predominantly focuses on the oncogenic role of SIRT5, with limited information on enhancing its expression to exert tumor-suppressive effects." (PMID 39944690, 2025). "The tumor-suppressive mechanism of SIRT5 is also related to antioxidant response." (PMID 39979670, 2025). "Additionally, this review offers new perspectives for tumor therapy and drug development, highlighting the potential of targeting SIRT5 and succinylation as innovative strategies for combating cancer." (PMID 39944690, 2025). "This difference suggests that while SIRT3 may contribute to tumor aggressiveness, SIRT5 may help protect against tumor development." (PMID 40710366, 2025). "In this study, we detected the expression of SIRT5 in normal and tumor tissues." (PMID 38532359, 2024). "In pancreatic ductal adenocarcinoma (PDAC), SIRT5 is a key tumor suppressor." (PMID 39479446, 2024). "Mechanistically, we hypothesized that SIRT5 exerts tumor-suppressive effects primarily through the regulation of mitochondrial metabolism." (PMID 39201811, 2024). "Furthermore, by desuccinylating serine SHMT2, which catalyzes the catabolism of serine and provides methyl for cellular methylation events through single-carbon metabolism, SIRT5 also contributes to the proliferation of tumor cells." (PMID 39479446, 2024). "Thus, SIRT5 has gained recognition as a critical tumor suppressor in PDAC, with its depletion markedly accelerating tumorigenesis and metabolic reprogramming." (PMID 39682281, 2024). "Our findings indicate a tumor-suppressive role for SIRT5 that extends beyond regulating cancer metabolism, by which it may function through modulating neuroplasticity." (PMID 39201811, 2024). "In addition, enhanced SIRT5 activity leads to cell cycle arrest of tumor cells in G1/S phase due to negative regulation of cell cycle protein-dependent kinase 2 (CDK2) and inhibition of glycolysis." (PMID 39479446, 2024). "Notably, SIRT5 oscillates between oncogenic and tumor-suppressive roles by regulating key metabolic enzymes; whereas, SIRT7 drives PCa proliferation and metabolic stress adaptation through its chromatin and nucleolar regulatory functions." (PMID 39796040, 2024). "There are few studies on the relationship between SIRT5 and tumor." (PMID 38773972, 2024). "Hence, SIRT5 overexpression results in lower amounts of protein succinylation and consequent impairment of tumor development both in vitro and in vivo." (PMID 36980194, 2023). "Based on the data above, we speculated that SIRT5 may be a potential biomarker of the ccRCC, which inhibits the growth of tumor." (PMID 37096064, 2023). "In addition, the use of a peptide-based SIRT5 inhibitor (see compound 8d, Section 4.2.2) highlighted the tumor suppressor function of SIRT5 by increasing PC-3 cell migration and invasion." (PMID 36980194, 2023). "Moreover, SIRT5 inhibition had no impact in A549 cells where wild-type PKM2 was replaced with the tumor-suppressing succinylation mimetic mutant K489E, bearing a negatively charged glutamate in place of the lysine residue targeted by SIRT5." (PMID 36980194, 2023). "Among them, SIRT5 seem to play important roles in tumor suppression." (PMID 37096064, 2023). "The inhibition of SIRT5 has demonstrated a reduction in cell proliferation and tumor growth, implying that hyper-succinylation may exert similar effects on tumor growth by modulating SIRT5." (PMID 37808079, 2023). "By interfering with many pathways, SIRT5 acts as a tumor promoter in a variety of malignancies." (PMID 36980194, 2023).
tumor (continued). "Recent studies have shown that SIRT5 depletion enhances glutamine and glutathione metabolism and promotes tumorigenesis through acetylation-mediated glutamate oxaloacetate transaminase 1 (GOT1) activation, while the SIRT5-selective activator MC3138 inhibits the proliferation of tumor cells." (PMID 37196115, 2023). "Moreover, SIRT5 has a protective function in the context of neurodegenerative diseases, while it acts as a context-dependent tumor promoter or suppressor." (PMID 36980194, 2023). "ASPSCR-1 and Sirt-5, which may be closely related to tumor migration had been identified, were selected according to the bioinformatics analysis." (PMID 37948465, 2023). "This is especially significant in cancer, because SIRT5 could serve as a tumor promoter or suppressor even in the same cancer subtype." (PMID 36980194, 2023). "In contrast to the decreased SIRT5 level in PCa tissues, the Ksu level in tissue samples from patients with T3 tumor stage was significantly increased compared to those from patients with T2 tumor stage (P < 0.01), as a result of the reduced desuccinylation activity." (PMID 35278714, 2023). "Although there is evidence of SIRT5 mRNA expression in a range of malignancies, many studies demonstrated that SIRT5 may act as either a tumor suppressor or a tumor promoter, depending on the specific pathways it regulates." (PMID 36980194, 2023). "Consequently, we believe that SIRT5 plays important role in tumor suppression, and closely related to better prognosis of patients with ccRCC." (PMID 37096064, 2023). "SIRT5 and 7 have been demonstrated to promote tumor progression in lung and breast cancers." (PMID 36577755, 2022). "This is particularly relevant in cancer, where SIRT5 may actas either tumor promoter or tumor suppressor even in the same cancertype." (PMID 35802779, 2022). "Moreover, SIRT5 has been proven to affect tumor development by regulating the expression levels of superoxide dismutase 1(SOD1) and citrate synthase (CS)." (PMID 36397343, 2022). "To conclude, these published data suggest that similar to SIRT4, SIRT5 might have a tumor suppressor function in GC." (PMID 36358890, 2022). "Furthermore, SIRT5 has pleiotropic roles in tumorigenesis, acting as a tumor suppressor or an oncogene via post-translational modifications, depending on cell conditions." (PMID 35889322, 2022). "We, therefore, speculated that SIRT5 suppression might considerably impact DNA synthesis in tumor cells." (PMID 36253417, 2022). "In the present study, low expression of SIRT5 was observed in DTC patients with advanced diseases and significantly correlated with improved DFS, suggesting SIRT5 may function as a tumor-suppressor gene." (PMID 35136826, 2022). "Furthermore, inhibiting SIRT5 with a peptide-basedinhibitor (compound 3d, section 4.1) increased PC-3 cell migration and invasion, thereby confirmingits tumor suppressive role in this context." (PMID 35802779, 2022). "Like SIRT3, studies have shown that SIRT5 can play a tumor-promoting or tumor-suppressing role." (PMID 36117172, 2022). "Increasing evidence shows tumor-promoting role of sirtuin-5 (SIRT5) in different cancers." (PMID 33921908, 2021). "The current findings demonstrate that SIRT5 may be involved in oxidative homeostasis and tumor development by regulating oxidative stress processes." (PMID 34257819, 2021). "Based on these data, we concluded that SIRT5 might be a tumor suppressor that is involved in ccRCC tumorigenesis by regulating cancer metabolism." (PMID 34930316, 2021). "Therefore, further studies of direct regulation between HIF‐1a and miRNAs or SIRT5 need to be broadened, and we will expound more upon the function of miR‐3677‐3p in different tumour microenvironments." (PMID 32596968, 2020). "However, the function of SIRT5 in tumorigenesis by regulating tumor microenvironment is poorly understood." (PMID 32953892, 2020).
tumor (continued). "Interestingly, the NAD+-dependent desuccinylase protein, SIRT5, has been shown to support proliferative tumor cell growth in in vitro as well as in vivo models." (PMID 33046741, 2020). "Furthermore, average tumor load, a sum of the diameters of all tumors, of Sirt5 KO mouse was significantly lower than that of WT mice." (PMID 32953892, 2020). "The expression of Sirt5 in tumor samples was slightly higher than paired normal tissues." (PMID 32953892, 2020). "Like Sirt1-3, Sirt5 was shown to have dual tumor suppressor and tumor promoter activities." (PMID 32698385, 2020). "Considering the side effects of lysosomotropic agent chloroquine and a decrease in chloroquine activity by tumour acidity, SIRT5‐mediated LDHB deacetylation pathway might be a new therapeutic target for treating CRC." (PMID 30443978, 2019). "We found that overexpression of SIRT5 promotes glutamine anabolic metabolism by activating GLUD1 in a deglutarylation-dependent manner, and is associated with CRC cell proliferation, survival, and xenograft tumor growth." (PMID 29416026, 2018). "In xenograft mouse models, overexpression of SIRT5 promoted tumor growth significantly." (PMID 29416026, 2018). "Moreover, inhibition of SIRT5 suppresses tumor cell proliferation through desuccinylation of PKM2 K498." (PMID 28036303, 2017). "The exact role of sirtuins in cancer remains controversial with dichotomous functions being reported, for example multiple studies have shown that SIRT1, SIRT3 and SIRT5 can act as tumor promoters or tumor suppressors under different cellular conditions, tumor stage and tissue of origin." (PMID 27465020, 2016). "This may be part of the mechanism behind SIRT3, SIRT4, and SIRT5 appearing to have tumor-suppressive effects." (PMID 25165814, 2014). "SIRT5 exhibits dual functionalities: it can promote tumor proliferation, metastasis, drug resistance, and metabolic reprogramming, thereby acting as an oncogene; conversely, it can also inhibit tumor cell growth and induce apoptosis, functioning as a tumor suppressor gene." (PMID 39944690, 2025). "Therefore, SIRT5 dysregulation can affect tumor development in several ways." (PMID 39781339, 2025). "Therefore, SIRT5 can inhibit tumor cell growth through interfering with multiple pathways." (PMID 39944690, 2025). "However, the specific functions of SIRT5 in different types of tumors remain to be further elucidated, particularly given its dual nature as a potential tumor suppressor in some contexts and a tumor promoter in others." (PMID 39944690, 2025). "Furthermore, SIRT5 expression levels were inversely correlated with the degree of tumor malignancy." (PMID 39201811, 2024). "However, their role in cancer remains unclear, with SIRT5 probably being the least understood in the context of tumor biology." (PMID 39201811, 2024). "Mitochondrial SIRTs (SIRT3, SIRT4 and SIRT5) have been widely reported to regulate a variety of key biological processes, including gene expression, DNA damage repair, metabolism and survival, and have the Janus role in tumorigenesis, either tumor suppressive or oncogenic functions 122-124." (PMID 38773972, 2024). "Consequently, SIRT5 is considered a pivotal regulator in various cancers and inhibitors targeted succinylation may serve as promising anti-tumor." (PMID 38882606, 2024). "Hence, by interfering with these pathways, SIRT5 inhibits the growth of tumor cells." (PMID 36980194, 2023). "However, SIRT5 also exerts a tumor-promoting function as a metabolic regulator." (PMID 36581622, 2022). "Furthermore, Sirt5 deletion PyMT mice had slower tumor growth and less metastasis." (PMID 34650436, 2021). "Interestingly, increased expression of SIRT5 predicted superior OS, and this may be partly due to its marked overexpression in early tumor stages." (PMID 31572453, 2019). "SIRT5 is associated with tumour pathological parameters but not patient outcome." (PMID 26121130, 2015).
tumor (continued). "SIRT5 desuccinylates K280 of SHMT2, upregulates its activity, prevents tumor growth, and is a novel mechanism to control cancer cell proliferation." (PMID 39979670, 2025). "In other studies, hypersuccinylation of SHMT2 through SIRT5 inhibition had been described to decrease SHMT2 activity and tumour growth." (PMID 40172090, 2025). "The researchers found that SIRT5 expression was significantly decreased in GBM tissues compared with normal tissues, indicating its potential role in tumor suppression." (PMID 40710366, 2025). "SIRT5 desuccinylates K498 of PKM2, downregulates enzymatic activity, and inhibits cell proliferation and tumor growth stimulated by oxidative stress." (PMID 39979670, 2025). "Sirtuin 5 (SIRT5), which is the only type III histone deacetylase lowly expressed in PCa, is a tumor suppressor of PCa." (PMID 39485722, 2024). "Mitochondrial sirtuins (SIRT3–SIRT5) regulate metabolism, with SIRT3 and SIRT4 acting generally as tumor suppressors, while SIRT5’s role remains ambiguous across caner types." (PMID 39796040, 2024). "Thus, we speculated that SIRT5 may be an important tumor suppressor gene." (PMID 37096064, 2023). "Altogether, SIRT5 silencing induces DNA damage in CRC via post-translational modifications and inhibits tumor growth, suggesting that SIRT5 can serve as a promising target for CRC treatment." (PMID 36253417, 2022). "Moreover, Sirt5 can regulate autophagy in the liver and in tumor cells, and Sirt5-knockout mice are characterized by an abnormal retinal electroretinogram and mitochondrial autophagy defects, suggesting that Sirt5 may be involved in the protection of retinal nerve function in DR." (PMID 35165261, 2022). "SIRT5 knockout MMTV-PyMT mice had higher survival and reduced tumor size and lung metastases compared to the SIRT5 wild-type MMTV-PyMT mice." (PMID 36291902, 2022). "In support of the SIRT5–TKT axis, TKT overexpression rescued SIRT5 silencing-induced decreased tumor volume and weight, downregulation of R5P and nucleotide levels, as well as DNA damage and cell apoptosis." (PMID 36253417, 2022). "SIRT5 catalyzes the desuccinylation of the serine metabolic enzyme SHMT2 to regulate one-carbon metabolism and promote tumor proliferation." (PMID 36577755, 2022). "Considering that SIRT5 is often overexpressed in CRCs, we established a subcutaneous xenograft tumor model in nude mice by injecting them with HCT116 cells stably expressing the control vector, SIRT5 WT, and SIRT5 H158Y." (PMID 36253417, 2022). "Overall, in this context, SIRT5 seems to play an oncogenicrole by impairing SUN2 activity and sustaining tumor growth via theWarburg effect." (PMID 35802779, 2022). "The expression levels of SIRT1, SIRT3, SIRT5, SIRT6, and SIRT7 were significantly correlated with tumor stage and histological grade." (PMID 32158696, 2020). "Remarkably, the xenograft study showed delayed tumor growth, as well as decreased tumor size and mass, when GLUD1 was inhibited in SIRT5-overexpressing tumors, which suggested that GLUD1 knockdown abolished SIRT5-induced tumor growth significantly in vivo." (PMID 29416026, 2018). "To address the oncogenic role of SIRT5 in vivo, we established a xenograft tumor model in nude mice with HCT116 cells stably expressing control vector, SIRT5 WT, and SIRT5 H158Y." (PMID 29416026, 2018). "Given that SIRT5 is found in relatively low levels in normal colonic mucosa and FHC cells, our findings highlight a tumor-specific metabolic vulnerability with a potential therapeutic application." (PMID 29416026, 2018). "SIRT5 desuccinylates at K351 of PDHA1 and increases PDC activity, thereby altering metabolic crosstalk with the TCA cycle, inhibiting the Warburg effect and suppressing tumor progression." (PMID 39979670, 2025). "The consistency of this metabolic brake across both tumor and nontumor settings underscores why cancer cells upregulate SIRT5 to erase malonylation and maintain metabolic flexibility." (PMID 41107644, 2025).
tumor (continued). "Conversely, in NK/T-cell lymphoma, SIRT5 functions as a tumor suppressor by desuccinylation and destabilization of glucose-6-phosphate isomerase (GPI), thereby inhibiting glycolytic flux and tumor growth." (PMID 41425553, 2025). "For instance, in clear cell renal cell carcinoma, SIRT5 promotes mitochondrial OXPHOS by desuccinylating enzymes such as pyruvate dehydrogenase complex E1α subunit (PDHA1), which shifts metabolism away from aerobic glycolysis and restrains tumor growth." (PMID 41304967, 2025). "In addition, HDAC7 and SIRT5 can also reduce STAT3 acetylation levels, promoting tumour apoptosis, whereas CBP and KAT6B, as acetyltransferases, can reverse this process." (PMID 39778006, 2025). "However, in hypoxic tumor cells, HIF-1α stability is enhanced through SIRT5-mediated desuccination of PPA2." (PMID 40164945, 2025). "This aligns with the idea that malonylation accumulation (due to a lack of SIRT5 “eraser” activity) pushes metabolic enzymes into a less active state, thereby blunting the Warburg effect and slowing tumor progression." (PMID 41107644, 2025). "Upregulation of CPT1A and downregulation of SIRT5 synergistically promotes S100A10-K47succ and fibrillin 1 (FBN1) K672succ, resulting in the accumulation of S100A10 and FBN1 in GC cells and further promoting tumor progression." (PMID 38882606, 2024). "Previous studies have demonstrated that SIRT5 can mediate the desuccinylation of several mitochondrial proteins, such as glutamate dehydrogenase (GDH), malate dehydrogenase, and citrate synthase (CS), which, in turn, affect metabolic processes in tumor cells." (PMID 38256128, 2024). "Targeting SIRT5 with inhibitors significantly suppresses tumor growth in mouse models without notable toxicity in normal cells." (PMID 38773972, 2024). "Sirtuin 5 (SIRT5) is increasingly recognized as a key regulator of cellular metabolism, which is commonly dysregulated in cancer cells, resulting in enhanced proliferation and tumor progression." (PMID 39201811, 2024). "Interestingly, using a pan-cancer dataset to study the expression of the succinylation regulators CPT1A, KAT2A, sirtuin 5 (SIRT 5), and SIRT7 showed that especially KAT2A was up-regulated in all types of tumours compared to healthy controls." (PMID 38213532, 2023). "HPA and RT-qPCR analysis of whether they are aberrantly expressed in OSCC showed that SIRT5 and HDAC3 were significantly upregulated in tumor tissues when compared with normal samples." (PMID 37705968, 2023). "However, SIRT5 can bind to PKM2, which desuccinylates PKM2 and reduces its activity, contributing to the proliferation of tumor cells." (PMID 36359005, 2022). "However, there is quite a consensus in the literature that HDAC4, HDAC7, HDAC9, SIRT2, and SIRT7 are upregulated in GC and seem to be pro-tumor factors, whereas SIRT4, SIRT5, and SIRT6, which are downregulated, seem to have a tumor suppressor function." (PMID 36358890, 2022). "Furthermore, qRT-PCR detection confirmed that the expressions of APCDD1L-AS1 and SIRT5 were lower, and the expressions of miR-1322, miR-1972 and miR-324-3p were significantly higher in Lv-shRNA-APCDD1L-AS1 tumor tissues than the Lv-NC tumor tissues." (PMID 33516270, 2021). "Western blotting confirmed the overexpression of SIRT5 WT and SIRT5 H158Y in the xenograft tumor lysates, and we did not observe a significant change in GLUD1 protein level." (PMID 29416026, 2018). "Additionally, several selective SIRT5 inhibitors (such as compounds 36, CG-220, CG-232, etc.)have not been further investigated for their anti-tumor activity and action mechanisms." (PMID 38773972, 2024). "Notably, reduced Sirt5 expression in PDAC cells promoted cancer cell proliferation, whereas enhancing Sirt5 expression or activating it through a SIRT5 activator, MC3138, restrained tumor growth." (PMID 38605962, 2024).